VIM (vimentin)
Diseases named in the same sentence as VIM in open-access papers (continued):
Sharing a sentence is not in itself a finding about the gene and the disease.
tumor (continued). "EMT is a pivotal driver of tumor metastasis, which is characterized by the upregulation of the expression of MMPs, vimentin, N-cadherin and α-SMA, accompanied by the downregulation of the expression of E-cadherin, occludins and cytokeratin." (PMID 31935687, 2020). "Immunohistochemical staining of paraffin sections for Vimentin allowed for accurately distinguishing between tumor cells (positive) and cells of the neuronal and glial host tissue (negative)." (PMID 32967361, 2020). "Vimentin is an interfilament protein involved in the epithelial–mesenchymal transition (EMT) process, which is a hallmark of metastatic tumor cells." (PMID 32466394, 2020). "E-cadherin-positive tumour cells transitioning to vimentin positivity (possibly remaining E-cadherin positive, see high magnification inset) were observed in EDW01 PDXs whereas VIM mRNA and protein in ED03 were almost negligible." (PMID 33276802, 2020). "In tumor cell areas, the median vimentin/cytokeratin index ratio was almost twice as high (0.28) as in the epithelial layer of oropharyngeal mucosa of control patients (0.15; p < 0.005)." (PMID 32630033, 2020). "The primary tumor and cells expressed high levels of VIM, as expected, and ALP, which has been shown to be expressed in mesenchymal stem cells." (PMID 32652895, 2020). "Our results further support a functional contribution of this vimentin-TF regulatory axis in providing tumor cells with enhanced coagulant properties and an increased competence to accomplish early metastasis." (PMID 32152404, 2020). "Among them, EMT, characterized by the downregulation of epithelial cell markers (E-cadherin and claudin-1) and upregulation of mesenchymal cell markers (N-cadherin and vimentin), is an early event in tumor metastasis." (PMID 32477134, 2020). "The vimentin overexpression in tumor endothelium shows a relationship with the CPMV uptake in tumor endothelial cells, as revealed in studies using the chick choreoallantoic membrane tumor model." (PMID 31936832, 2020). "Conversely, downregulation of vimentin not only hampers the migration of a large variety of tumor cell lines but also partially restores their epithelial phenotype." (PMID 31940801, 2020). "The most relevant cellular component of the tumor stroma are activated fibroblasts, characterized by an increased expression of α-smooth muscle actin (αSMA) and vimentin, a change from the fusiform to stellate shape, and enhanced ECM production." (PMID 32178458, 2020). "Herein, our results showed that tumor AUB-PrC cells demonstrate some vimentin (mesenchymal cell marker) expression as well." (PMID 33195205, 2020). "The results of one-way ANOVA analysis showed a remarkable difference of Vimentin gene expression in ETE and RTR groups (P<0.05) so that Vimentin expression had decreased significantly in tumor tissue of the ETE group (F=270/85, P=0.0001)." (PMID 32405368, 2020). "This is a noteworthy finding, considering vimentin correlation with high tumor growth rate, invasiveness and poor prognosis." (PMID 32204402, 2020). "Immunofluorescence staining in the SCK xenograft tumor tissue indicated significantly increased E-cadherin and decreased N-cadherin, snail, and vimentin protein levels after GEM implantation compared with the control tumors." (PMID 32111094, 2020). "The tumor tissues showed a higher Ki67 and Vimentin intensity in the linc00514-OVE group than that in the control group, indicating a more aggressive ability of the linc00514-overexpressing MDA-MB-468 cells." (PMID 32943090, 2020). "Normal stroma in most organs contains a small number of quiescent or resting fibroblasts, whereas reactive tumor stroma is generally characterized by an increased number of activated fibroblasts that express αSMA, vimentin and FAP." (PMID 33260828, 2020). "Results showed that the expression of vimentin significantly increased in high-level circPTK2 tumor tissue and obviously decreased in low-level circPTK2 tumor tissue." (PMID 31973707, 2020).
tumor (continued). "Here, we found that FN assembled on the ESCC tumor cell membrane was highly associated with low expression level of miR-146a, which led to increased ESCC cell invasion through increased vimentin expression." (PMID 33248456, 2020). "In summary, we show that Galectin-3 modulated angiogenesis- and EMT-driven metastasis via activation of the β-catenin signalling cascade by targeting IGFBP3 and vimentin in the HCC tumour microenvironment." (PMID 32801345, 2020). "Western blotting results indicated that the protein level of BRD4, c-Myc, CyclinD1, CDK4, MMP-2, MMP-9, Vimentin and N-cadherin were all decreased while E-cadherin was increased in the tumor with circCELSR1 knockdown." (PMID 32640974, 2020). "N-cadherin-positivity, vimentin-positivity, mesenchymal and partial EMT phenotypes were associated with more aggressive tumor characteristics such as triple-negative subtype." (PMID 32300922, 2020). "Vimentin, a mesenchymal marker, enables tumor cells to delaminate from the primary tumor and invade locally." (PMID 32612946, 2020). "To do that, we determined the level of expression of vimentin and N-cadherin in tumor samples of 67NR cells." (PMID 32922123, 2020). "Tumor growth was particularly promoted by the LKB1G135R mutant which also showed increased production of vimentin." (PMID 32647375, 2020). "Vimentin is overexpressed in most epithelial cancers and its levels correlate with tumor migration, invasion, and poor prognosis." (PMID 32985606, 2020). "Histopathological examinations on tumor sections showed DCXNLS2-mut tumor tissue displayed less amount of Vimentin and GFAP staining compared with DCX-vector via IHC." (PMID 32050972, 2020). "The cell-membranous expression of E-cadherin and both the cytoplasmic and cell-membranous expression of β-catenin were present in the tumor cells, whereas vimentin was expressed in the tumor-related stromal tissue cells." (PMID 32794417, 2020). "The percentage of cytokeratin/vimentin double-positive cells was 2.65 ± 2.35% in the tumor cell areas." (PMID 32630033, 2020). "When the expression level of Vimentin in tumor cells is increased and overwhelming keratin as the main component of the cytoskeleton, epithelial-mesenchymal transition (EMT) occurs, playing a substantial role in tumor invasion and metastasis." (PMID 32194806, 2020). "In this review, we focus mainly on tumor marker vimentin IFs in the context of epithelial-to-mesenchymal transition (EMT), cell migration, and invasion." (PMID 31940801, 2020). "The mRNA levels of CSCs markers (CD44 and CD24) and EMT markers (E-cadherin, β-catenin, vimentin, and N-cadherin) in tumor tissues were analyzed with qRT-PCR." (PMID 33282946, 2020). "Unexpectedly, PLS3 and vimentin expression levels were lower in tumor tissues than in normal tissues (p < 0.001)." (PMID 31947504, 2020). "In the SGRh2-administered group, the immunostaining analysis of xenografted tumour tissues revealed that E-cadherin protein was increased and Ki67, N-cadherin, and Vimentin protein was reduced." (PMID 32141497, 2020). "The latest report shows that vimentin or EMT can affect the infiltration of immune cells in tumor microenvironment." (PMID 32850341, 2020). "Tumor cells were diffusely positive for vimentin, human melanin black (HMB)‐45, and melanocyte‐differentiation‐antigens MART‐1 (Melan A) via immunohistochemistry obtained from both lesions." (PMID 32803839, 2020). "Clusters #2 and 3, which had high expression of mesenchymal genes including Vimentin, Timp1, and Twist1, were predominantly composed of recurrent tumor cells but had small populations of primary tumor cells." (PMID 33024122, 2020). "McElwee reported that overexpression of PADI2 in mice led to occur EMT in tumor cells, which decreased E-Cadherin expression and increased Snail and Vimentin expression." (PMID 32951601, 2020).
tumor (continued). "We further evaluated the expression of Wnt1, β‐catenin, EMT markers (E‐cadherin and vimentin) and stemness‐associated markers (CD133, Nanog and Oct4) in xenograft tumours." (PMID 33026174, 2020). "Some of them are of particular interest—for example, vimentin (VIME) involved in the positioning of organelles is a marker of the epithelial-mesenchymal transition of tumor cells." (PMID 32708613, 2020). "The expression levels of miR-146a and vimentin in the second set of 68 paired ESCC patient specimens (non-tumor vs. tumor) in the tissue array (Group II) were measured by ISH and IHC staining." (PMID 33248456, 2020). "Vimentin staining was positive in the tumor cell cytoplasm of xenografts co-injected with MSC-CA located in the invasive front." (PMID 32093026, 2020). "The tumor cells showed diffuse positivity for S-100 and vimentin and focal positivity for epithelial membrane antigen (EMA)." (PMID 32212579, 2020). "Hematoxylin staining together with anti-human antibodies against Ki67 and tumor marker vimentin was further performed to confirm the human origin of tumor growth on the CAM." (PMID 33037240, 2020). "The remaining 240 proteins were considered tumor-related differentially expressed proteins and included Vimentin, β-catenin, HLA-A/B/C, and MICA, among others." (PMID 33173143, 2020). "PTs with a positive N-cadherin, positive vimentin, mesenchymal or partial EMT status were associated with more aggressive tumor characteristics, exemplified by the triple-negative subtype." (PMID 32300922, 2020). "For instance, pairwise comparison of primary tumor cell line #1 with recurrent tumor cell line #3 identified a cluster (Cluster #7) distinguished by high expression of mesenchymal genes, including Vimentin, S100A6, and Timp1." (PMID 33024122, 2020). "We detected high E-cadherin expression in tumor epithelial cells undergoing collective invasive (red circle), but low E-cadherin and Vimentin expression in EOC orthotopic xenograft tumor models with AAV9/GFP/LRRC4." (PMID 32117780, 2020). "Accordingly, down-regulation of SPP1 reduced tumor cells invasion and vimentin expression, but increased the level of GFAP, a marker of differentiated astrocytes." (PMID 33066172, 2020). "We considered samples to be positive for vimentin when expression was observed in more than 10% of tumor cells." (PMID 32106476, 2020). "The presence of vascular endothelial cells (CD31+), immune cells (CD45+), macrophages (IBA-1+), and vimentin+mesenchymal cells in the tumor stroma was confirmed by immunostaining." (PMID 32435696, 2020). "Certainly, in our tissue culture model, double vimentin-cytokeratin immunostaining demonstrated this mesenchymal transition of tumor cells." (PMID 32388727, 2020). "In this study, expression of vimentin, immune checkpoint molecules (PD-1 and PD-L1), tumor-infiltrating CD8+ T cells, and regulatory T cells (Tregs) were assessed by immunohistochemical staining to reflect immune status in RCC." (PMID 32850341, 2020). "We performed immunohistochemical staining to measure the expression of MACROD2, p-GSK-3β, β-catenin, and the EMT markers E-cadherin, vimentin, and N-cadherin in primary tumor tissues from the 380 patients in the FFPE cohort." (PMID 32257385, 2020). "In this study, EMT was quantified in HNC tumor samples by the cellular co-localization of cytokeratin/vimentin, E-cadherin/β-catenin and by Slug expression." (PMID 32630033, 2020). "The results of immunohistochemical investigation revealed that tumor cells stained positive for CD31, CD34, VI antigen, and vimentin which confirmed the endothelial origin of the tumor." (PMID 31906980, 2020). "We used EpCAM (for epithelial phenotype) and Vimentin (for mesenchymal phenotype), in addition to PanCK (tumor marker), CD45 (leukocyte marker), and DAPI (nuclear marker)." (PMID 31947893, 2020).
tumor (continued). "OC treatment also showed antimetastatic activity in vivo, which was associated with significant increase of E-cadherin and remarkable decrease of vimentin expressions in collected tumor sample lysates at the study end." (PMID 32545325, 2020). "Immunohistochemically, tumour cells were intensely and diffusely positive for vimentin, as expected for a tumour of mesenchymal tissue origin, and variably positive for α-SMA and desmin." (PMID 32787426, 2020). "According to the increased E-Cadherin level, a decrease of Vimentin expression, the mesenchymal marker, is measured in both tumor cells lines, especially in MDA-MB-231." (PMID 32340282, 2020). "On the other hand, tumor cells with mesenchymal attributes that have passed an epithelial-mesenchymal transition (EMT) express proteins like vimentin." (PMID 32466213, 2020). "As EMT and MMPs are closely associated with the increased migration and invasion capacity of tumor cells, EMT-associated markers, E-cadherin, N-cadherin, vimentin and transcription factors, Snail and Twist, were detected by RT-qPCR." (PMID 32699531, 2020). "We here report a novel EMT-driven regulatory mechanism of TF expression in tumor cells by which vimentin protects TF mRNA from a miR-dependent downregulation." (PMID 32152404, 2020). "Previous studies reported that TGF-β-mediated ETM regulates the expression of vimentin, supporting tumor aggressiveness." (PMID 31952346, 2020). "Immunohistochemically, tumor cells in all 21 cases showed diffuse immunostaining for vimentin, SMA, MSA, and calponin." (PMID 32337257, 2020). "Immunohistochemically, the tumor cells were diffusely positive for Vimentin, and partially positive for epithelial membrane antigen (EMA) with at least moderate intensity, which was mainly expressed in epithelioid cells." (PMID 31915021, 2020). "The expression pattern of CIRC tumors is a challenge for pathologists, as several neoplasms express cytokeratins and vimentin, which can result in confusion." (PMID 32979929, 2020). "The ubiquitination site was localized at residue K439 in vimentin amino acid sequence, and its ubiquitination level was significantly decreased with a ratio of T/N (tumor/control) = 0.36 in LSCCs compared to controls." (PMID 32140187, 2020). "Low PCDHGA9 expression was frequently correlated with low E-cadherin expression and high N-cadherin, Vimentin and Twist expression in tumour tissues." (PMID 32231199, 2020). "The expression of E-cadherin was decreased and vimentin wasincreased, the two important markers in the tumor EMT process." (PMID 33335992, 2020). "Results showed that E-cadherin increased with the increase of tumor differentiation, while N-cadherin and vimentin decreased." (PMID 32477006, 2020). "A similar observation can be made with the downregulation of hsa-miRNA-203 (hsa-miRNA-203a or hsa-miRNA-203b), which was associated with VIM and SNAI1 upregulation and CDH1 downregulation in NSCLC tumor tissues." (PMID 32438606, 2020). "Immunophenotypically, the tumor was positive for vimentin, epithelial membrane antigen (EMA) and negative for CK-pan, CAM5.2, CD31, CD34, smooth muscle actin (SMA), desmin, anaplastic lymphoma kinase (ALK), calponin, TTF-1 and S-100 protein." (PMID 32039736, 2020). "Based on the screening, we chose six highest and six lowest circPTK2-expressing tumor tissue for the further functional assays, and we detected the expression level of vimentin in three highest and three lowest circPTK2-expressing tumor tissues by IHC." (PMID 31973707, 2020). "To this end, we detected the EMT markers in tumor tissues and found that the mesenchymal marker vimentin was down-regulated, and the epithelial marker E-cadherin was up-regulated when the 4 T1 cell was inoculated in C3aR−/− mice." (PMID 31931851, 2020). "We collected metastatic tumour tissues and analysed the tissue histology to confirm tumour metastasis and detected the expression of miR-17-5p and Vimentin as a mesenchymal marker." (PMID 32546833, 2020).
tumor (continued). "By virtue of the unique mechanical properties of vimentin, vimentin IFs provide transformed cells with elasticity and contribute to the vicious cycle of tumor tissue stiffening." (PMID 31940801, 2020). "Tumoral-cells were ER and PR positive, HER2 negative, and associated stromal cells were positive for vimentin expression when tested." (PMID 33203195, 2020). "Vimentin is a major indicator of cancer cell ability to migrate from primary tumor and invade to surrounding tissue." (PMID 32728167, 2020). "The percentage of Slug-positive cells in tumor cell areas correlated positively with the percentage of cytokeratin/vimentin double-positive cells (r = 0.41; R2 = 0.17; p = 0.005)." (PMID 32630033, 2020). "EGF also has been shown to reduce E-cadherin expression and increase Vimentin expression in a variety types of tumor cells." (PMID 32376896, 2020). "IHC staining of a neovascularization marker (CD31) and EMT markers (E-cadherin and Vimentin) in tumor tissues provided the similar expression trajectories of EMT and angiogenesis presented by GM1." (PMID 32612211, 2020). "Vimentin silencing also decreased the ability of tumor cells to accomplish metastatic colonization when injected as CTCs in experimental metastasis assays." (PMID 32152404, 2020). "Most tumor cells are strongly positive for vimentin; CD99 and Bcl-2 are also expressed in some cells." (PMID 32011484, 2020). "IHC analysis demonstrated that tumor cells was Vimentin (+), α-Inhibin (+), CD99 (+), Calretinin (+), SF-1(+), AE1/AE3 (+), CD10 (+), ER (+), PR (+), AFP (−), EMA (−), SMA (−), CK7 (−), Ki-67 (+60%)." (PMID 32629665, 2020). "Over-expression of vimentin correlates with increased tumor growth and invasiveness, and as well as with poor clinical outcomes in several cancers." (PMID 33330495, 2020). "Co-IF staining of PanCK and vimentin showed an ongoing stable expression of cytokeratin until day 21, even within the highly invasive tumor front." (PMID 32824777, 2020). "The presence of tumor cells positive for both E-cadherin and vimentin suggests that partial EMT occurs in the original tumor, PDX model, and spheroids." (PMID 32546182, 2020). "Silencing vimentin indeed inhibited the coagulant properties of tumor cells and co-transfecting the TSB1 attenuated this effect." (PMID 32152404, 2020). "Vimentin attaches to the nucleus, ER, and mitochondria and is expressed in malignant cells during the epithelial‐mesenchymal transition (which increases tumor aggressiveness)." (PMID 32590878, 2020). "The role of expression of epithelial markers such as E-cadherin, the phenomenon of cadherin switch and overexpression of mesenchymal markers (like Snail, Twist, ZEB1/2, Slug and VIM) has been shown across tumor models." (PMID 32758253, 2020). "It is known that upregulation of vimentin is a marker of epithelial-mesenchymal transition, which indicates an increase in the ability of tumor cells to migrate and invade and, therefore, tumor ability to metastasize." (PMID 32842595, 2020). "In these instances, vimentin expression has been associated with epithelial to mesenchymal transition (EMT), a biological process associated with tumour invasiveness." (PMID 32102337, 2020). "Histological analysis revealed that the expression of YAP1, TAZ and vimentin was higher and the expression of E‐cadherin was reduced in the tumour tissues of hyperglycaemic mice (P < .05)." (PMID 32678516, 2020). "As EMT is one of the key events in tumor cell chemoresistance, we examined the epithelial markers (E-cadherin) and mesenchymal markers (vimentin) with western blotting." (PMID 32071552, 2020). "Recently, one study demonstrated both circulating tumor cells exhibiting an active EMT status (vimentin+ and EGFR+) and tumoral expression of AXL mRNA as prognostic factors for OS and RFS of patients with early stage resectable NSCLC." (PMID 32674274, 2020). "Immunohistochemistry analysis revealed the tumor cells being positive for vimentin and vascular CD31." (PMID 32299394, 2020).